EGFR (epidermal growth factor receptor)
Diseases named in the same sentence as EGFR in open-access papers (continued):
Sharing a sentence is not in itself a finding about the gene and the disease.
cancer (continued). "On the other hand, YAPon cancers exhibited increased sensitivity to inhibitors targeting tyrosine kinases (e.g., SRC, ERBB, and EGFR) or serine/threonine kinases (e.g., BRAF)." (PMID 38067201, 2023). "A variety of short interfering RNAs (siRNAs), as well as miRNAs have been tested for anti-cancer effects in HCC cells in vitro, targeting the major components of the EGFR/PI3K/AKT/mTOR signaling pathway." (PMID 37631344, 2023). "Lipid raft disruption can alter the positioning and function of signaling molecules like EGFR and HER2 that play a role in cancer cell proliferation and survival." (PMID 37446908, 2023). "In this study, we analyzed in detail the evolutionary dynamics of two major cancer axes: Notch/WNT/Hedgehog and AKT/mTOR/EGFR." (PMID 37174700, 2023). "In other cancer cell types, cetuximab proved to be effective in KRAS wild-type, EGFR-expressing gastric cancer cell line NCI-N87 and xenografts." (PMID 38201251, 2023). "Despite the extensive research and ongoing studies, inhibiting the cross-talk between the EGFR and MET signaling pathways in cancer remains a challenge." (PMID 37631372, 2023). "Panitumumab is an IgG2 monoclonal antibody that binds to EGFR, blocking the binding of VEGFR and VEGF and inhibiting cancer cell growth." (PMID 37614311, 2023). "Tumour metastasis is defining characteristic of advanced cancer stage, TAM-derived EGF accelerates metastasis by activating the EGFR-ERK signaling and inhibiting the expression of lncRNA LIMT in the epithelial ovarian cancer." (PMID 37965573, 2023). "Similar results were observed in another two tested models, one model involving MET-amplified MKN45 cancer cells with stable SYK knockdown and one model involving EGFR-mutant PC9 cells with stable SYK knockdown." (PMID 37183231, 2023). "If we assume all EGFR T790M and RET fusion discovered from NGS in this study can be detected by other cheaper PCR‐based analyses, 30 (50%) patients' cancer will be targetable." (PMID 38140788, 2023). "Synthesized SOXs (4a–h) were further subjected to the drug-likeness, ADME, and in silico screening for their inhibitory efficacy against cancer-specific molecular markers, i.e., CD44, AKR1D1, HER-2, and EGFR." (PMID 37108498, 2023). "The epidermal growth factor receptor (EGFR), a tyrosine kinase receptor of the ErbB/HER oncogene, is among the cancer-related targets." (PMID 36831545, 2023). "From the network pharmacology analysis, it was found that the main targets for inhibiting BPH are AKT1, TNF, EGFR, STAT3 and PTGS2, which are enriched in pathways in cancer." (PMID 37446563, 2023). "Third, in cluster C, we observed changes in acetylation of transcriptional regulatory proteins (e.g., histones) that are suggestive of widespread transcriptional down-regulation in response to TKIs in both EGFR- and ALK-driven cancer cells." (PMID 36996232, 2023). "As described in further investigations, EGCG was tested in various types of cancer cells, usually with the outcome indicating that EGCG blocks the EGFR pathway via binding with the EGFR receptor." (PMID 37446908, 2023). "The Hh signaling pathway has been shown to crosstalk with other oncogenic pathways in many cancer types, such as RAS/RAF/MEK/ERK, PI3K/Akt, EGFR, and Notch." (PMID 37853413, 2023). "In in vitro studies, the co-stimulation of EGF and HGF (hepatocyte growth factor) showed a synergistic effect on cell proliferation in cancer cells expressing both MET and EGFR (epidermal growth factor receptor)." (PMID 38137393, 2023). "RTKs and GPCRs can act independently to alter cancer growth; however, NTSR1 regulates the tyrosine phosphorylation of RTKs such as the EGFR." (PMID 37508387, 2023). "Gefitinib, an epidermal growth factor receptor (EGFR) inhibitor with quinazolinamine moiety, was reported to inhibit BCRP but also modulate the function of P-gp in multidrug-resistant cancer cells." (PMID 36830622, 2023).
cancer (continued). "Cancer treatments aim to modulate cellular pathways essential for cancer survival and growth, such as RAS, EGFR, vascular endothelial growth factor VEGF, and MMPs." (PMID 36831374, 2023). "Epidermal growth factor receptor (EGFR) is frequently seen during invasion and development of many malignant tumors." (PMID 37285389, 2023). "It is worth noting that in various biological systems, TGFα has been shown to be a more powerful agonist for EGFR than EGF23,24, indicating the potential importance of TGFα in regulating cancer progression." (PMID 37821657, 2023). "The most significant cancer-related pathways regulated by asporin are FGF2, TGF-β1, BMP-2, epidermal growth factor receptor (EGFR) and CD44." (PMID 36765749, 2023). "Although it is well known that the correlation between EGFR signaling and TGF-β expression in many cancers." (PMID 37601668, 2023). "Consistently, we unveiled that the majority of the cancer samples concomitantly expressing the highest levels of CBX3 and EGFR specifically show higher occurrence in EGFR high-grade amplification coupled to low-gain increase in CBX3 gene CN." (PMID 37633946, 2023). "In other cancers, NUAK1 expression also positively correlates with EGFR expression and Akt Ser-473 phosphorylation." (PMID 38135881, 2023). "Cetuximab binds specifically to EGFR and competitively blocks VEGF and other receptors, inhibiting intracellular signaling pathways, thereby suppressing the proliferation of cancer cells and inducing apoptosis." (PMID 37614311, 2023). "EGFR was found to be expressed by Treg cells, and the AREG-EGFR signaling axis is critical for maintaining Foxp3 stability in Treg cells in patients with cancer." (PMID 37611111, 2023). "Deregulated EGFR expression is present in various cancers, including CRC, and increased EGFR expression is present in 25‒77% of CRC." (PMID 37639911, 2023). "Like varlitinib, lapatinib is a dual TKI targeting both EGFR and HER2 and is currently used to treat cancer." (PMID 37601068, 2023). "These signature included EGFR, COX2, and the matrix metalloproteinases 1 (MMP1), CXCL1 and IDI1 which were highly expressed in the Triple Negative subtype and HER2-positive cancers." (PMID 36761968, 2023). "It is important to note that candidalysin can indirectly activate the epidermal growth factor receptor (EGFR), a complex mechanism involving EGFR and matrix metalloproteinase (MMP) ligands, which are involved in many types of cancer." (PMID 37374978, 2023). "The EGFR-mediated ERK, PI3K/Akt, and STAT signaling pathways play a crucial role in cancer metastasis." (PMID 36770659, 2023). "EGFR and its downstream signaling pathways are involved in the proliferation, migration, and epithelial-mesenchymal transition (EMT) of various cancer cells." (PMID 37644107, 2023). "For example, cancer markers such as CD91, CD317, and epidermal growth factor receptor (EGFR) are detected as membrane proteins on C-EVs, and a panel of 12 miRNAs was detected in EVs as RNA markers." (PMID 36834913, 2023). "In response to epidermal growth factor (EGF) and its activated receptor (EGFR), PPAR β/δ protein levels and stability are increased via the recruitment of HSP90 (heat shock protein 90) in cancer cell lines." (PMID 37048084, 2023). "Our study reveals a previously unidentified AREG/EGFR-mediated Treg/CAF coupling that controls the bifurcation of fibroblast functional states and is a critical barrier for cancer immunotherapy." (PMID 37611111, 2023). "AREG/EGFR-mediated Treg/CAF coupling controls bifurcation of CAF and is a critical barrier for cancer immunotherapy." (PMID 37611111, 2023).
cancer (continued). "PDGFRβ in CAFs can interact with PDGF-BB expressed by cervical cancer cells and promote cancer cell growth by upregulating the expression of heparin-binding epidermal growth factor (HB-EGF) and activating the EGFR signaling pathway." (PMID 37143134, 2023). "LC3B upregulation in NANOG promotes immune resistance through stimulating over-activation of EGFR signaling, and the NANOG-LC3B-EGFR axis is a key factor in controlling NANOG immune-refractory cancers as a central molecular target." (PMID 37422448, 2023). "Whereas by modulating of signalling pathway, it inhibits the activation of epidermal growth factor receptor (EGFR) pathway, which is known to play a crucial role in the growth and survival of cancer cells." (PMID 37803407, 2023). "Activated EGFR pathways and downstream MEK/ERK signaling were reported to promote AXL mRNA expression through the JUN transcription factor in a number of cancer cells." (PMID 37047640, 2023). "After binding with ligands, EGFR triggers the phosphorylation of downstream pathways, such as MAPK, PI3K-AKT, JAK-STAT, and PLCγ1-PKC pathways, mainly supporting cancer cell survival and proliferation." (PMID 37020674, 2023). "We investigated the utility of PIP-seq for understanding cancer dynamics by first validating the single-cell transcriptional responses of two cancer cell lines (H1975 and PC9) to gefitinib, an epidermal growth factor receptor (EGFR) tyrosine kinase inhibitor." (PMID 36879006, 2023). "The combined inhibition of EGFR and VEGF using erlotinib and bevacizumab showed similar anti-cancer effects in patients with advanced HCC (NCT00881751)." (PMID 37631344, 2023). "We obtained the data for the combinations of daunorubicin with EGFR and HDAC inhibitors in 60 cancer cell lines." (PMID 37629110, 2023). "Dual inhibition of EGFR and NOTCH2/3 reduces EGFR and radiation-induced cancer stem cell subpopulations, as well as the expression of DNA repair genes." (PMID 37444584, 2023). "In the case that the cancer cells acquire resistance to ADT as CRPC, however, the expression of HS3ST1 and 3-OS HS is upregulated, facilitating the binding of EGF and HB-EGF to EGFR via 3-OS HS." (PMID 37463954, 2023). "The gene therapy using Ad-FZ33 with anti-EpCAM or anti-EGFR or anti-CEA antibodies is a potentially effective and safe therapeutic strategy for various cancers." (PMID 36678816, 2023). "Overactivation of the EGFR and downstream cascades, including MEK/ERK and PI3K/Akt, is frequent in cancer." (PMID 37516013, 2023). "The most prevalent altered cancer-related genes were CTNNB1 (16%) and ZNRF3 (16%), followed by EGFR (11%), JARID2 (11%), KMT2B (11%), KMT2C (11%), NSD1 (11%), PIK3CA (11%), SH2B3 (11%), and UBR5 (11%)." (PMID 38023213, 2023). "The anti-cancer potential of kaempferol was facilitated by the blockage of ERK1/2, EGFR-related Src and AKT pathways." (PMID 37239974, 2023). "In an animal model, TH revealed chemopreventive properties by decreasing cancer cell proliferation and activity, as seen by a reduction in the expression of cancer-related genes such as CCND1, EGFR, and COX-2." (PMID 36830249, 2023). "Gefitinib, an EGFR TKI, has been used as a treatment in different human cancers (colon, ovary, and breast)." (PMID 38069386, 2023). "In oncogene-addicted cancers (HER2-mutant cancer, oncogene-driven EGFR-positive, ALK-positive, or RET-positive NSCLC), current studies do not encourage the use of immune checkpoint inhibitors, with the exception of KRAS-mutated cancers." (PMID 36865093, 2023). "The aim of this review is to present accumulating evidence that epidermal growth factor receptor (EGFR) signaling, often dysregulated in cancer, is also an emerging signaling pathway critically involved in pain and opioid tolerance." (PMID 38004424, 2023). "In the TME, ANG is expressed by cancer cells, EGFR is expressed mostly by cancer cells and to a lesser extent by fibroblasts, and PLXNB2 is expressed mainly by dendritic cells, macrophages, and cancer cells." (PMID 38025776, 2023).
cancer (continued). "The mechanisms underlying EGFR–TKI resistance in NSCLC can be broadly categorized into acquired resistance following EGFR–TKI treatment and primary resistance characterized by cancer cells relying on alternative oncogenes like KRAS." (PMID 37816585, 2023). "Studies have indicated elevated expression of NaPi2b in diverse cancers, especially notable in lung cancer patients exhibiting TTF1 positivity along with mutants in KRAS and EGFR." (PMID 38162667, 2023). "Different molecules such as EGFR, PTEN, V-ATPase, syndecan 1 and galectin-3 play distinct roles in the metabolic regulation of RAS-mediated macropinocytosis in cancer." (PMID 37535087, 2023). "We observe the transient interaction between activated EGFR and HER2 molecules at the cell membrane of cancer cells in real time." (PMID 36781849, 2023). "Members of the ErbB family (EGFR, HER2, HER3, and HER4) of receptor tyrosine kinases (RTK) are key targets in cancer therapy." (PMID 37153618, 2023). "Phosphorylation of EGFR activates the downstream components including ERK, PI3K/Akt, and STAT signaling pathways, which play a crucial role in cancer metastasis." (PMID 36770659, 2023). "To examine the effects of long‐term exposure on cancer cells, we cultured A549 and H1975 cells in the presence of PM2.5 at 50 μg/ml for 90 days before analysis of proliferation and EGFR activation." (PMID 36975376, 2023). "The best compounds identified from the in vitro assays on EGFR (i.e.15 and 18) were also tested for their antiproliferative activity towards the H1975 NSCLC cancer cell lines expressing the double mutant, obtaining satisfactory results." (PMID 36373202, 2023). "Thus, this study highlights the unique therapeutic potential of AuNP-NmAb in the EGFR+ target-specific treatment of cancers and promotes further studies involving clinical applications of AuNP-carrier-based mAb therapeutics for enhanced efficacy of mAbs against cancers." (PMID 37623652, 2023). "On the other hand, in hormone-independent VCap cells, EGFR, AR, and Matrix Metalloproteinase-9 (MMP-9) are reported to cooperate to promote cancer progression." (PMID 37463954, 2023). "Nonetheless, there is a rather general consensus on the correlation between EGFR expression levels, poor prognosis and worse treatment outcomes in patients with HNSCC, while there is no definitive evidence that EGFR gene copy number and mutations may have prognostic value in this group of cancers." (PMID 36817764, 2023). "EGF/EGFR interact with the MEK-ERK and AKT-PI3K signaling pathways, which leads to cancer cell proliferation." (PMID 37853413, 2023). "Development of inhibitors that target EGFR/RAS/ARF/MEK/ERK pathway is considered an effective and promising strategy for the clinical treatment of numerous cancers." (PMID 36755950, 2023). "Since TOPO II and the epidermal growth factor receptor (EGFR) mutually influence expression, targeting them simultaneously emerges as a promising anti-cancer approach." (PMID 37895927, 2023). "Antibody dependent cellular cytotoxicity (ADCC) is one of the important MOA of many monoclonal antibody cancer therapies, including HerceptinTM (against HER2) and ErbituxTM (against EGFR)." (PMID 36602988, 2023). "In specific cancers like non-small cell lung cancers and melanoma, HDAC6 plays a crucial role by increasing the stability of proteins like EGFR and tubulin β3." (PMID 38067304, 2023). "Although immunotherapy with immune checkpoint inhibitors (ICIs) induces sustained cancer remission in a subset of NSCLCs, ICI therapy exhibits limited activity in most EGFR-mutant NSCLCs." (PMID 38001917, 2023). "The colocalization coefficients (GIC) of clathrin and EGFR, clathrin and AP2 and EGFR and AP2 all showed a significant increase in cancer compared to normal (p = 0.0125, p = 0.0125, p = 0.0128, respectively)." (PMID 36869937, 2023).
cancer (continued). "The release of these ligands subsequently activates EGFR and triggers both the mitogen-activated protein kinase (MAPK)/PI3K and Akt pathway in cancer cells, leading to increased proliferation and angiogenesis." (PMID 37393260, 2023). "Here, toward deciphering the mechanisms whereby GRP78 knockdown suppresses EGFR transcription, we find that nuclear GRP78 is prominent in cancer and stressed cells and uncover a nuclear localization signal critical for its translocation and nuclear activity." (PMID 37487081, 2023). "These cancers all have in common epidermal growth factor (EGF) receptor overexpression/amplification, such as EGFR and ERBB2." (PMID 38041118, 2023). "Our data show that adapter-tethered EGFR and ERBB2 fusions are capable of sustaining cancer cell growth and proliferation and, importantly, are sensitive to inhibition with EGFR and/or HER2 inhibitors." (PMID 37168365, 2023). "Nanotechnologies used to enhance the efficacy of anticancer drugs such cisplatin, paclitaxel and cetuximab, EGFR antagonists, MEK1/2 and immune check inhibitors combination showed promising anti-cancer activity." (PMID 37189730, 2023). "Cetuximab is a monoclonal antibody that targets the epidermal growth factor receptor (EGFR), a protein overexpressed in cancer cells." (PMID 37675170, 2023). "In conclusion, we demonstrated that the elevated activated PKG I by 8-Br-cGMP can interact with EGFR and disrupt its downstream MEK/ERK pathway related to cancer progression." (PMID 36653376, 2023). "It is also theorized that a loss of upstream regulators such as MST1/2, LATS1/2, and NF2 and signaling pathways such as EGFR, PI4K/Akt, and RAS/RAF/MEK/ERK promote YAP/TAZ activity in cancer." (PMID 37444578, 2023). "Similar to EGFR antagonists, ADAM10 inhibitors are tested as anti-cancer drugs in randomized clinical trials." (PMID 37967063, 2023). "In line with this, CD27xEGFR demonstrated selective and simultaneous binding to EGFR and CD27, with clear doublet formation of carcinoma and T cells and inhibition of binding upon pre-incubation with excess amounts of mAb 425 and CD27 mAb." (PMID 37545491, 2023). "An EGFR-targeted chitosan NP was created to silence the Mad2 gene using small interfering RNAs (siRNAs) in patients with A549 cell line NSCLC (epithelial carcinoma derived from a 58-year-old male patient, known to be KRAS mutant and EGFR wild type)." (PMID 37754880, 2023). "The overexpression of EGFR and EGF‐like peptides is common in human carcinomas, and evidence has shown that these proteins promote cell transformation in vitro and in vivo." (PMID 37042307, 2023). "The epidermal growth factor receptor (EGFR) pathway plays a key role in tumorigenesis, cancer cell survival, migration, angiogenesis and apoptosis." (PMID 36307775, 2022).